FGFR3 (fibroblast growth factor receptor 3)
Diseases named in the same sentence as FGFR3 in open-access papers (continued):
Sharing a sentence is not in itself a finding about the gene and the disease.
bladder cancer (continued). "In this study, the results of the integrated bioinformatical analysis suggested FGFR3 as a possible indicator for TME status remodeling and clinical outcomes such as distant metastasis, overall survival rate, and immunotherapy response to bladder cancer." (PMID 35991125, 2022). "Human anti-FGFR3 mAb, MFGR1877S (Genentech), is a monoclonal antibody against FGFR3 and has been used against multiple myeloma and MFGR1877S and has also shown antitumour activity for overexpressed FGFR3 in preclinical models of bladder cancer." (PMID 34830836, 2021). "Besides, ERBB3, FGFR3, CTLA4, and LAG3 are also reported in some studies as potential therapeutic targets for bladder cancer." (PMID 34026819, 2021). "Moreover, circRNA hsa_circ_0068871 regulates FGFR3 expression and activates STAT3 by targeting miR-181a-5p to promote bladder cancer progression, showing some of the important roles of circRNA in BC." (PMID 32460831, 2020). "To further investigate whether low MATH value in FGFR3-mutant patients is widely applicable to predict better overall survival in BLCA, we selected another BLCA cohort which was composed of 109 bladder cancer patients published in 2015." (PMID 33243261, 2020). "Studies have shown the potential prognostic value of markers including receptor tyrosine kinases such as fibroblast growth factor receptor 3 (FGFR3), epidermal growth factor receptor (EGFR), and ERBB2/human epidermal growth factor receptor 2 (HER2) in invasive bladder cancers." (PMID 33312739, 2020). "Some studies have focused on activating FGFR1 and FGFR3 in bladder cancer; however, other FGFRs and FGF-ligands were not studied." (PMID 31369573, 2019). "As FGFR 3, another member of FGFR family, can increase angiogenesis and influence the prognosis in bladder cancer, other members in the FGFR family may also influence the outcome or tumor severity of UCC." (PMID 31878098, 2019). "Approximately 10% of bladder cancer cases harbor mutations in RAS genes, such as HRAS, KRAS and NRAS, which do not occur with FGFR3 mutations." (PMID 29614760, 2018). "This regulation of FGFR3 by MYC seemed to be quite specific to bladder cancer, because MYC binding to the FGFR3 enhancers or promoter was rarely observed in a publicly available dataset encompassing 118 MYC chromatin immunoprecipitation and sequencing (ChIP‐Seq) in different tissues." (PMID 29463565, 2018). "Thus, it was very essential to explore the correlations among FGFR3, KIAA1377, POLA2, and EPHA4 in bladder cancer, as well as other cancers or diseases." (PMID 28320388, 2017). "The GSE41035 dataset downloaded from Gene Expression Omnibus was used to identify the differentially expressed genes (DEGs) between bladder cancer cell line RT112 with or without depletion of FGFR3, and gene ontology enrichment analysis was performed." (PMID 28320388, 2017). "Using microarray data generated from bladder cancer cell line, RT112, with inducible knockdown of FGFR3 from three different shFGFR3 sequences, we found that DAPK1 expression was upregulated by knockdown of FGFR3 in inducible conditions for all the three different shFGFR3 sequences (p < 0.001)." (PMID 28388658, 2017). "In conclusion, we analyzed gene expression profiles of the bladder cancer cell line RT112 with or without depletion of FGFR3 and conducted further analyses using a computational bioinformatics approach based on the publicly available data." (PMID 28320388, 2017). "Aberrant activation of fibroblast growth factor receptor 3 (FGFR3) is frequently observed in bladder cancer, but how it involved in carcinogenesis is not well understood." (PMID 28320388, 2017).
bladder cancer (continued). "Our findings are consistent with the results of the TCGA data set for the “squamous-like” subtype of bladder cancer (n = 85), which revealed reduced overall expression of FGFR1 and FGFR2 in tumors compared to normal tissue, while expression of FGFR3 remained high." (PMID 27669755, 2016). "FGFR3 is an essential partner of the transforming FGFR3-TACC3 fusion, but findings of potential tumor suppressive properties in pancreatic cells and bladder cancers suggested that FGFR3 might exhibit different effects in terms of different tissues." (PMID 27829236, 2016). "FGFR3 and TAK1 alter gene expression in Bladder Cancer cells." (PMID 24466111, 2014). "Activation of FGFR3 is thought to result in the stimulation of the Ras/Raf/MEK/ERK pathway (also known as the mitogen activated protein kinase pathway) and the PI3K/Akt pathway in bladder cancer." (PMID 24944696, 2014). "Finally, our data show that FGFR3 and FGFR1 are expressed by the “epithelial” and “mesenchymal” subsets of bladder cancer cells, respectively." (PMID 23468956, 2013). "Similarly, bladder cancer cell lines (UCC) subjected to hypoxia exhibited lower levels of miR-100, which targets fibroblast growth factor receptor 3 (FGFR3)." (PMID 24152442, 2013). "Furthermore, marked heterogeneity in their responses to FGFR inhibitors has been noted, and not all FGFR3 altered bladder cancer cells exhibit response." (PMID 39031286, 2024). "Unlike bladder carcinomas, the most affected genes are FGFR3, HRAS, and KMT2D." (PMID 39064555, 2024). "Studies involving FGFR3 activated bladder cancer cell lines show major inhibition of p-ERK but not p-AKT following FGFR inhibitor treatment, which suggests that the MAPK pathway could be the major downstream signaling pathway that is activated." (PMID 39031286, 2024). "Considering bladder cancer is not among the most common cancers and has a relatively good prognosis, it may therefore not be justified to target FGFR3 specifically to prevent bladder cancer." (PMID 38684708, 2024). "Combination treatment strategy for FGFR3 and NEDD4 could be useful for bladder cancer." (PMID 36733484, 2023). "Hence, this study suggests that FGFR3 may be a potential target that can influence survival and immunotherapy response and remodel TME in bladder cancer patients." (PMID 35991125, 2022). "Similarly, these genes were also modulated by ETV5 in the invasive bladder cancer cell line 97-7, but not in the non-invasive FGFR3-mutant cell lines, MGHU3 and UMUC14." (PMID 30952872, 2019). "We also showed that MYC upregulated FGFR3 expression directly, by binding to enhancers upstream from FGFR3, as part of a FGFR3/MYC positive feedback loop operating both in vitro and in vivo in bladder cancer‐derived cell lines xenografts and in a PDX model bearing an FGFR3 mutation." (PMID 29463565, 2018). "Although oncogenic FGF receptor 3 (FGFR3)-BAIAP2L1 fusion gene has been identified in bladder cancers and lung cancers, we could not detect the transcript of fusion genes of BAIAP2L1 in this study of a limited number of specimens." (PMID 26222696, 2015). "FGFR fusions with oncogenic activity have been previously identified in bladder cancer (FGFR3), lymphoma (FGFR1 and FGFR3), acute myeloid leukemia (FGFR1), multiple myeloma, myeloproliferative neoplasms, and most recently glioblastoma multiforme (FGFR1 and FGFR3)." (PMID 24550739, 2014).
bladder cancer (continued). "Elevated phosphorylation of AKT1/2 is observed in 40–50% of bladder cancer cases, independent of PIK3CA or PTEN alterations, and may result from upstream receptor tyrosine kinase (e.g., FGFR3 or EGFR) activation." (PMID 41438986, 2025). "Nonetheless, to our knowledge, no prior work has examined how FGFR3 alterations functionally affect the tumor microenvironment, nor how acute FGFR inhibition may cooperate with ICI in FGFR3-altered bladder cancer." (PMID 38226620, 2024).
achondroplasia (260 papers, 2006 to 2026). "Achondroplasia, associated with gain-of-function mutations in FGFR3, causes growth plate cartilage dysfunction, resulting in short-limb dwarfism." (PMID 41748604, 2026). "Our data suggest that dysregulation of Wnt/β-catenin activity due to Fgfr3 gain-of function mutation constitutes an important underlying mechanism in craniofacial defects observed in achondroplasia." (PMID 41954527, 2026). "Achondroplasia is the most common genetic skeletal dysplasia, caused by activating mutations in the FGFR3 gene that impair endochondral ossification and result in disproportionate short stature." (PMID 40821249, 2025). "Achondroplasia is the most common form of skeletal dysplasia, caused by an activating mutation in the fibroblast growth factor receptor 3 (FGFR3) gene." (PMID 39998583, 2025). "Achondroplasia is the most common skeletal dysplasia (SD) caused by an activating fibroblast growth factor receptor-3 mutation (FGFR-3), with a prevalence of 1 in 20 000–30 000 live births." (PMID 41140768, 2025). "Achondroplasia is a genetic condition caused by constitutively activated FGFR3 signaling, resulting in inhibition of endochondral ossification." (PMID 41340868, 2025). "Achondroplasia, the most prevalent short-stature disorder, is caused by missense variants overactivating the fibroblast growth factor receptor 3 (FGFR3)." (PMID 39817451, 2025). "The NIPT results at 18 weeks’ gestation detected the fetal FGFR3 pathogenic variant c.1138G > A (p.Gly380Arg), consistent with achondroplasia." (PMID 39813116, 2025). "Caused by a variant in the fibroblast growth factor receptor 3 (FGFR3) gene, the worldwide birth prevalence of achondroplasia is estimated to be approximately 3.72–4.6 per 100,000." (PMID 40375310, 2025). "Achondroplasia, caused by a FGFR3 mutation, results in rhizomelic shortening, metaphyseal flaring, and characteristic genu varum from both extra-articular bowing and intra-articular degeneration." (PMID 41140768, 2025). "Achondroplasia is caused by a gain-of-function mutation in the fibroblast growth factor receptor 3 (FGFR3) gene, which encodes a transmembrane tyrosine kinase receptor that plays a role in chondrocyte proliferation and differentiation." (PMID 40821249, 2025). "Achondroplasia is a rare genetic disease caused by a recurrent gain-of-function mutation of the fibroblast growth factor receptor 3 (FGFR3) gene, with a global prevalence of approximately 250,000 people." (PMID 41194157, 2025). "Pathogenic FGFR3 variants cause achondroplasia, an autosomal dominant skeletal disorder with an incidence of 2–3 cases per 100,000 people." (PMID 40567897, 2025). "Achondroplasia is a rare genetic condition caused by mutations in the fibroblast growth factor receptor 3 (FGFR3) gene, which regulates bone growth and results in abnormal cartilage formation, particularly in the long bones." (PMID 40520800, 2025). "Mutations in FGFR3, including those observed in achondroplasia, result in a cell surface receptor that is both ligand-dependent and ligand-independent." (PMID 40821249, 2025). "Achondroplasia, characterized by short stature and skeletal abnormalities, is caused by a gain-of-function variant in the fibroblast growth factor receptor 3 gene." (PMID 38841012, 2024). "Achondroplasia is an inherited genetic disorder caused by autosomal dominant gain-of-function pathogenic variants in the fibroblast growth factor receptor 3 gene (FGFR3) located on the short arm of chromosome 4." (PMID 39590755, 2024). "Achondroplasia is caused by gain-of-function variants in FGFR3, which negatively impacts the growth of long bones by inhibiting chondrocyte proliferation and differentiation in the growth plate." (PMID 39243045, 2024). "TD is part of a spectrum of dysplasias associated with FGFR3 mutations, including achondroplasia and hypochondroplasia, which serve as differential diagnoses." (PMID 39493014, 2024).
achondroplasia (continued). "We present a case of a female patient initially diagnosed with achondroplasia due to a maternally inherited pathogenic FGFR3 variant." (PMID 39243045, 2024). "Achondroplasia is caused by mutations (G1138A and G1138C) in the fibroblast growth factor receptor 3 (FGFR3) gene located on chromosome 4p16.3." (PMID 39062241, 2024). "Achondroplasia is an autosomal dominant genetic disorder caused by pathogenic variants in fibroblast growth factor receptor 3 (FGFR3; HGNC: 3690) gene." (PMID 39669637, 2024). "The main cause of achondroplasia is a de novo mutation in fibroblast growth factor receptor-3 (FGFR3), which leads to a disruption of the endochondral ossification mechanism." (PMID 38265860, 2024). "Clinical suspicion included hypochondroplasia/achondroplasia caused by FGFR3-related skeletal dysplasia." (PMID 40225944, 2024). "When initiating treatment with vosoritide, the PBS requires that the patient must have a diagnosis of achondroplasia, confirmed by appropriate genetic testing for FGFR3 mutations that are associated with achondroplasia." (PMID 39062238, 2024). "Achondroplasia, caused by autosomal dominant mutations in the fibroblast growth factor receptor 3 (FGFR3) gene, results in short stature and a variety of clinical manifestations that negatively impact health and quality of life throughout the lifespan." (PMID 38078681, 2024). "In achondroplasia, FGFR3 mutations cause disruptions in the ossification of the skull base, thus affecting the shape and size of the foramen magnum and posterior fossa, explaining the Chiari phenotype." (PMID 39458107, 2024). "In humans, the most common genetic cause of achondroplasia (dwarfism) is caused by a substitution mutation in the FGF receptor FGFR3, one of the receptors for FGF4." (PMID 38397188, 2024). "A 3-year-old girl with disproportionate short stature was initially diagnosed with achondroplasia due to a maternally inherited pathogenic FGFR3 variant (FGFR3, NM_000142.5: c.1138G > A, p.Gly380Arg), that also affected her older brother." (PMID 39243045, 2024). "Many are caused by mutations in several FGFRs, including FGFR3 (achondroplasia) and FGFR2 (Apert, Crouzon, and Pfeiffer syndromes)." (PMID 39459551, 2024). "Achondroplasia is caused by autosomal dominant mutations in the fibroblast growth factor receptor 3 (FGFR3 gene), hindering the normal process of endochondral bone growth." (PMID 38610900, 2024). "Boer and colleagues were able to extract nuclear DNA from a premolar and identified the Gly380Arg mutation of the FGFR3 gene, which is pathognomonic for achondroplasia." (PMID 39044201, 2024). "Individuals with hypochondroplasia have different genetic variants in FGFR3 than those seen in individuals with achondroplasia, although their clinical spectrums can overlap, with hypochondroplasia generally being less severe." (PMID 38813446, 2024). "For instance, FGFR3: c.1138G>A (p.G380R) mutation accounted for 90% of the condition in achondroplasia patients, while the FGFR3: c.1620C>A (p.N540K) mutation occurred in 70% of individuals with hypochondroplasia." (PMID 38318287, 2023). "We identified a heterozygous variant of the FGFR3 gene as the rare pathogenic variant of severe achondroplasia in a fetus." (PMID 37076826, 2023). "Achondroplasia (ACH) is a skeletal dysplasia characterized by shortened limb stature caused by gain-of-function mutations in fibroblast growth factor receptor 3 (FGFR3)." (PMID 37428729, 2023). "While FGFR3 gain of function mutations lead to short stature (achondroplasia, ACH, MIM #100800 and hypochondroplasia, HCH, MIM #146000), FGFR3 loss of function mutations cause camptodactyly, tall stature, and hearing loss syndrome (CATSHLS, MIM #610474)." (PMID 38152138, 2023). "FGFR3 is a causative gene for achondroplasia in humans, and is expressed by cells in bones and cartilages, including proliferating chondrocytes in the growth plate and periosteal cells in the metaphyseal region." (PMID 37185464, 2023).